UQCRHP1 (ubiquinol-cytochrome c reductase hinge protein pseudogene 1)
Synonyms: Em:AF129756.18; UQCRHP5
Gene: Transcribed processed pseudogene on chromosome 6 (31,611,083 to 31,611,356, reverse strand). Ensembl gene ENSG00000230622.
Diseases named in the same sentence as UQCRHP1 in open-access papers:
UQCRHP1 is named in the same sentence as 1 disease in open-access papers, as found by Europe PMC text mining. Sharing a sentence is not in itself a finding about the gene and the disease.
UQCRHP1 shares sentences with these, for which no sentence is quoted: infection (1 paper).